TBC1D10B (TBC1 domain family member 10B)
Description:
Acts as a GTPase-activating protein for RAB3A, RAB22A, RAB27A, and RAB35. Does not act on RAB2A and RAB6A.
Synonyms: FP2461; DKFZP434P1750; Rab27A-GAPbeta; FLJ13130; EPI64B
Tractability: Antibody: UniProt places it where antibodies can reach, with high confidence; its Gene Ontology location is reachable by antibodies, with high confidence. PROTAC: ubiquitination databases record sites on it; its protein half-life has been measured.
Gene: Protein-coding gene on chromosome 16 (30,357,102 to 30,370,529, reverse strand). Ensembl gene ENSG00000169221.
Subcellular location: Cytoplasm; Cell membrane
Pathways (Reactome):
Vesicle-mediated transport: TBC/RABGAPs
Gene Ontology:
Molecular function: GTPase activator activity; protein binding
Biological process: regulation of cilium assembly; regulation of GTPase activity; retrograde transport, endosome to Golgi
Cellular component: cytoplasm; plasma membrane; cytosol
Genetic constraint (gnomAD): Loss-of-function variants: 25 observed, 66.24 expected, observed/expected ratio (o/e) 0.38, 90% interval 0.27 to 0.53. The synonymous counts are far from expectation, so gnomAD's model fits this gene poorly and the ratio says little. Missense variants: 996 observed, 973.75 expected, observed/expected ratio (o/e) 1.02, 90% interval 0.97 to 1.08. Synonymous variants: 517 observed, 423.67 expected, observed/expected ratio (o/e) 1.22, 90% interval 1.13 to 1.31.
Homologues: Orthologues: chimpanzee TBC1D10B (99% identical), macaque TBC1D10B (98% identical), dog TBC1D10B (92% identical), rat Tbc1d10b (89% identical), rabbit TBC1D10B (89% identical), mouse Tbc1d10b (88% identical), pig TBC1D10B (80% identical), tropical clawed frog tbc1d10b (56% identical), zebrafish tbc1d10b (50% identical). Paralogues in human: TBC1D10A (36% identical), TBC1D10C (25% identical), TBC1D2 (17% identical), TBC1D2B (17% identical), EVI5 (17% identical), EVI5L (17% identical), RABGAP1 (17% identical), RABGAP1L (17% identical), TBC1D4 (17% identical), TBC1D9B (16% identical), TBC1D1 (16% identical), TBC1D9 (15% identical), and 33 more.
Diseases named in the same sentence as TBC1D10B in open-access papers:
TBC1D10B is named in the same sentence as 10 diseases in open-access papers, as found by Europe PMC text mining. Sharing a sentence is not in itself a finding about the gene and the disease. The quoted sentences say what the papers report.
gastric adenocarcinoma (2 papers, 2022 to 2023). "Even though overexpression of TBC1D10B has been reported to promote tumor invasion and metastasis in gastric adenocarcinoma, the prognostic value of TBC1D10B and its correlation with DNA methylation and immune infiltration in hepatocellular carcinoma are still not known." (PMID 36611046, 2023).
breast carcinoma (1 paper, 2023). "In our study, the TBC1D10B expression in most common cancers, including breast cancer and lung adenocarcinoma, was significantly elevated." (PMID 36611046, 2023).
hepatocellular carcinoma (1 paper, 2023). A malignant tumor that arises from hepatocytes. "This study found that TBC1D10B is highly expressed in hepatocellular carcinoma and that increased TBC1D10B mRNA expression is associated with female sex, lower Body Mass Index, high level of alpha fetal protein, and worse clinical stages." (PMID 36611046, 2023). "We also found that the methylation of TBC1D10B was associated with the prognosis in patients with hepatocellular carcinoma." (PMID 36611046, 2023). "Transcriptional expression profiles of TBC1D10B between hepatocellular carcinoma tissues and normal tissues were downloaded from The Cancer Genome Atlas and Gene Expression Omnibus." (PMID 36611046, 2023). "Kaplan–Meier survival analysis showed that hepatocellular carcinoma patients with high TBC1D10B had a worse prognosis than those with low TBC1D10B, especially in patients with a weight below 70 kg, height above 170 cm, and histological G2 and G3." (PMID 36611046, 2023). "Our study indicates that increased TBC1D10B expression in hepatocellular carcinoma may play a role in tumorigenesis by regulating the cell cycle and extracellular matrix." (PMID 36611046, 2023). "TBC1D10B may be a novel prognostic and predictive marker and immune therapeutic target in hepatocellular carcinoma patients." (PMID 36611046, 2023). "Our research suggests that TBC1D10B may be regarded as a novel prognostic and predictive marker and therapeutic target for hepatocellular carcinoma patients, including RNA-targeting treatment, such as antisense oligonucleotides or RNA-targeting Cas9." (PMID 36611046, 2023).
Hyperglycemia (1 paper, 2023). An increased concentration of glucose in the blood. "Thus, additional studies are warranted to fully understand how NP-6A4-AT2R signaling suppresses Rictor and TBC1D10B and the role of these molecules in AT2R-induced cardioprotective autophagy in obesity and hyperglycemia." (PMID 37408206, 2023).
cancer (2 papers, 2022 to 2023). A tumor composed of atypical neoplastic, often pleomorphic cells that invade other tissues. "TBC1D10B-associated DEGs were also enriched in cancer pathways." (PMID 36611046, 2023). "More importantly, TBC1D10B-associated DEGs were associated with extracellular matrix (ECM) regulation and the MET gene, which were usually involved in both development and cancer progression." (PMID 36611046, 2023). "We compared TBC1D10B mRNA expression levels in different cancers based on TCGA data." (PMID 36611046, 2023). "The discordance between protein and mRNA levels indicates that the elevated RNA levels of TBC1D10B may be common, but they may not correlate with actual total protein expression or responses to certain cancer types." (PMID 36611046, 2023). "Unfortunately, whether dysregulation of TBC1D10B occurs following cancer occurrence has not been fully revealed." (PMID 36611046, 2023). "For the positive–negative subjects (screening), 3 CNAs were detected in BC genes (ACVR2A, CUL3 and PIK3R1), and 5 SNPs were identified in 6 non-BC cancer genes (SNIP1, TBC1D10B, PANK1, PRKCA and RUNX2; SUPT3H)." (PMID 35589867, 2022).
tumor (2 papers, 2023 to 2024). "Tumor properties, including PMI and growth, were suppressed, while tumor progression was increased by miR-3619-5 through the down-regulation of its downstream gene, TBC1D10B." (PMID 39641053, 2024). "A paired data analysis of tumor and matched nearby tissue from TCGA and GEO showed increased TBC1D10B mRNA in LIHC." (PMID 36611046, 2023). "The association between TBC1D10B mRNA expression and immune cell infiltration was investigated by the TIMER2 web server, tumor immune estimation resource and single-sample GSEA." (PMID 36611046, 2023). "We observed that TBC1D10B displayed a differential expression pattern in groups categorized according to simplified tumor stage and sample type." (PMID 36611046, 2023). "The Clinical Proteomic Tumor Analysis Consortium and the Human Protein Atlas were used to assess the TBC1D10B protein expression." (PMID 36611046, 2023). "Therefore, the roles and functions of TBC1D10B need to be further studied to provide a new strategy for tumor immunotherapy." (PMID 36611046, 2023). "However, the observed changes in TBC1D10B protein in LIHC were not due to parallel changes in TBC1D10B RNA levels, and no TBC1D10B expression was detected by immunohistochemistry in normal and tumor tissues." (PMID 36611046, 2023).
TBC1D10B also shares sentences with these, for which no sentence is quoted: liver cancer (1 paper); lung adenocarcinoma (1); Obesity (1); psychosis (1).